KLK6 (kallikrein related peptidase 6)
Diseases named in the same sentence as KLK6 in open-access papers (continued):
Sharing a sentence is not in itself a finding about the gene and the disease.
Alzheimer disease (14 papers, 2002 to 2025). A progressive, neurodegenerative disease characterized by loss of function and death of nerve cells in several areas of the brain leading to loss of cognitive function such as memory and language. "It was previously shown to be involved in proteolysis of extracellular proteins implicated in neurodegenerative diseases such as Alzheimer’s disease (AD), prompting validation of KLK6 as a potential biomarker of disease." (PMID 29378650, 2018). "Our transcriptomic study revealed an important upregulation of the Klk6 gene that encodes kallikrein-related peptidase 6, which is a biomarker of Alzheimer's disease." (PMID 26035870, 2015). "KLK6 has been involved in the regulation of myelin sheath volume and degradation of a β-amyloid peptide, a function associated to different neurodegenerative diseases such as Alzheimer’s disease, in which it has been proposed as a biomarker." (PMID 32655372, 2020). "KLK6 is involved in the regulation of neuronal function and the breakdown of amyloid-beta plaques in Alzheimer's disease." (PMID 41250190, 2025). "In Alzheimer’s disease (AD), KLK6-8 and 10 have been suggested as AD biomarker candidates, with CSF studies indicating elevated KLK6 and KLK10 in biomarker-confirmed cases, while KLK8 remains largely unchanged and KLK7 is decreased." (PMID 41516101, 2025). "Kallikrein-6 (KLK6) predicts the onset of neurocognitive decline in Alzheimer’s disease (AD), vascular dementia, and subarachnoid hemorrhages." (PMID 36289630, 2022). "On the other hand, altered levels of KLK6 in the brain and serum of people affected by Alzheimer’s disease and Parkinson’s disease have been documented, pointing out to its function in amyloid metabolism and development of synucleinopathies." (PMID 32655372, 2020). "There is a decrease of KLK6 protein in the serum of patients with Alzheimer’s disease compared to control patients of the same age." (PMID 32655372, 2020). "Studies of KLK6 levels in the CSF are still limited and conflicting, showing both low and high levels of KLK6 in the Alzheimer’s disease CSF samples." (PMID 27186164, 2016). "Recent studies have reported a role of KLK6 in the regulation of membrane-dependent signaling processes, and in neurodegenerative diseases such as Alzheimer's disease and Parkinson's disease." (PMID 27863404, 2016). "Several other studies found decreased levels of KLK6 in Alzheimer’s disease brain regions (e.g. parietal and frontal cortex)." (PMID 27186164, 2016). "There is convincing evidence from the literature on Alzheimer's disease that KLK6, the most abundant kallikrein-related peptidase in the central nervous system, cleaves the amyloid precursor protein (APP), a transmembrane glycoprotein from which Aβ derives." (PMID 26783378, 2015). "Downregulated serum levels of this biomarker predicted cognitive and motor declines in patients with Parkinson disease, Last, plasma levels of the neuroinflammation modulator KLK6 were significantly increased in patients with advanced Alzheimer disease compared with healthy controls." (PMID 39658124, 2024). "The expression of KLK6 in central nervous system (CNS) diseases is heterogeneous, such as upregulation of KLK6 expression in CNS inflammatory response and downregulation of KLK6 expression in Alzheimer’s disease (AD) and Parkinson’s disease." (PMID 34915845, 2021). "It has been suggested that KLK6 may process APP and this way contributes to Alzheimer’s disease pathology." (PMID 27186164, 2016). "Furthermore, the brain of Alzheimer’s disease patients contains significantly lower KLK6 levels than the brain of nonaffected individuals; when the mRNA levels were quantified in the hippocampus they were also decreased." (PMID 32655372, 2020).
Alzheimer disease (continued). "Besides all the information referring to KLK6 and KLK8, such as their aberrant expression in Alzheimer’s disease and dementia, a recent study expanded the KLKs contribution in CNS disorders by showing that the brain of Alzheimer’s disease patients presents decreased KLK7 mRNA expression." (PMID 32655372, 2020). "Nevertheless, it has recently been reported that KLK6 levels in cerebrospinal fluid (CSF) are significantly increased in patients with Alzheimer’s disease and elevated CSF phosphorylated tau (p-Tau), but not in Alzheimer’s disease patients with normal CSF p-Tau levels." (PMID 32655372, 2020).
colorectal cancer (14 papers, 2013 to 2025). A primary or metastatic malignant neoplasm that affects the colon or rectum. "Presence of KLK6 transcripts in lymph nodes of colorectal cancer (CRC) patients was associated with the shorter average survival time after surgery and was more sensitive indicator of poor prognosis than carcinoembryonic antigen (CEA)." (PMID 34065672, 2021). "Kallikrein-related peptidase 6 (KLK6) overexpression is commonly observed in primary tumors of colorectal cancer (CRC) patients and has been associated with tumor aggressiveness, metastasis, and poor prognosis." (PMID 31692974, 2019). "Interestingly, in our recent analysis of the molecular pathways associated with KLK6 overexpression in colorectal cancer we observed altered expression in laminin receptor and integrin 4B." (PMID 35883559, 2022). "Similarly, KLK6 mRNA overexpression in colorectal cancer is associated with serosal invasion, liver metastasis, and advanced Dukes’ stage, again being an unfavorable predictor of overall survival." (PMID 29229980, 2017). "KLK6 expression is associated with an unfavorable prognosis in ovarian and colorectal cancers." (PMID 26231762, 2015). "The role of KLK6 in colorectal cancer and the critical functions of KLK6 enzyme in CRC advancement to the late stages have been demonstrated in vitro and in vivo." (PMID 35883559, 2022). "KLK6, one of the 15 KLK family members, is a promising biomarker for diagnosis of many cancers and has been associated with poor prognosis of colorectal cancer (CRC) patients." (PMID 35883559, 2022). "Further studies are thus warranted to evaluate the role of other pathways in KLK6 induction in colorectal cancers." (PMID 35883559, 2022). "The aim of our study was to analyze The Cancer Genome Atlas (TCGA) RNA-Seq data from the colorectal cancer samples with high KLK6 expression with the goal to define KLK6-specific gene signature in the CRC for identification of potential markers of tumor progression in colorectal metastatic disease." (PMID 34065672, 2021).
melanoma (12 papers, 2011 to 2026). A malignant, usually aggressive tumor composed of atypical, neoplastic melanocytes. "For this analysis, we subcutaneously injected B16F10 melanoma cells into KLK6−/− mice, which showed low tumor growth." (PMID 36552865, 2022). "In the current study, we provide experimental evidence indicating a potential role played by KLK6 in cross-talk between melanoma cells and macrophages in the tumor microenvironment." (PMID 36552865, 2022). "We measured the TNF-α and IFN-γ levels in the supernatants of WT and KLK6−/− BMDMs after being co-cultured with B16F10 melanoma cells." (PMID 36552865, 2022). "CXCL1 mRNA levels and secretion increased in B16F10 melanoma treated with the CM of KLK6 overexpressed-RAW264.7 cells= compared to the CM of control vector-transfected cells." (PMID 36552865, 2022). "We provide experimental evidence indicating a potential role played by KLK6 in cross-talk between melanoma cells and macrophages in the tumor microenvironment." (PMID 36552865, 2022). "In human melanoma tissues, KLK6 expression was found in the stroma area in the inflammatory TME and was associated with the activation of PAR1, triggering intracellular calcium flux and tumour cell invasion." (PMID 34439122, 2021). "Our findings showed that the well studied KLK7 and other hKLK members (KLK6, 8 and 13) were coordinately expressed during melanoma progression: These findings were also validated in an independent dataset." (PMID 22032772, 2011). "Next, we treated with the CM of WT or KLK6−/− BMDM into B16F10 melanoma cells." (PMID 36552865, 2022). "In this work, we observed that the overall survival outcome was significantly associated with a high level of PDGFA and a low level of KLK6 and KLK10 expression in melanoma tumors and that these genes were expressed in an opposite way in XP patients who developed melanoma at a young age." (PMID 35974070, 2022). "In support of this hypothesis, it was shown that KLK6 is highly expressed in primary melanoma, which points to its involvement in the neoplastic processes and malignant progression." (PMID 35974070, 2022). "Indeed, it has been shown that KLK6, 7, 8, and 13 are co‐ordinately expressed in melanoma progression." (PMID 28636767, 2017). "Compared with wild-type mice, KLK6−/− mice showed less tumor growth and metastasis in the B16F10 melanoma and Lewis lung carcinoma (LLC) xenograft model." (PMID 36552865, 2022). "We subcutaneously injected B16F10 melanoma or LLC lung cancer cells into WT and KLK6−/− mice to investigate the effects of KLK6 on tumor growth in vivo." (PMID 36552865, 2022). "Another serine protease, called kallikrein-related peptidase 6 (KLK6), was shown to increase melanoma invasion though a Matrigel scaffold when released by supporting stromal cells." (PMID 36005056, 2022). "To identify the secreted factors that regulate KLK6-mediated malignant progression, we used mouse cytokine arrays for serum samples from WT and KLK6−/− mice injected with B16F10 melanoma cells." (PMID 36552865, 2022). "Our study showed that only 69% of the analyzed melanoma cell lines ectopically express KLK7, whereas KLK14 and KLK6 are expressed by almost all of the cell lines." (PMID 28636767, 2017). "In melanoma cells, PAR1 is activated by KLK6 promoting intracellular calcium flux and tumor cell invasion." (PMID 26231762, 2015). "The present study confirms these associations at the transcriptional level and shows that not only KLK6 and KLK7 but other hKLKs such as KLK8 and KLK13 are probably coordinately involved in melanoma progression." (PMID 22032772, 2011). "Further exploration with larger sample size is required to confirm the current findings and to examine the consequences of the altered transcriptional profile especially concerning KLK6 and KLK10 who may contribute to the worsening of Melanoma tumorigenesis." (PMID 35974070, 2022).
melanoma (continued). "On the other hand, KLK6 expression is not detected in melanomas but is observed in keratinocytes and stromal cells adjacent to benign nevi, primary melanomas, and cutaneous metastatic lesions." (PMID 36552865, 2022). "RT-PCR and ELISA data showed that CXCL1 mRNA levels and secretion in B16F10 melanoma significantly increased on coculture with WT BMDMs but not with KLK6−/− BMDMs." (PMID 36552865, 2022). "Although KLK6 was not detectable in cutaneous melanoma cells, a strong KLK6 protein expression was found in keratinocytes and stromal cells located adjacent to benign nevi, primary melanomas, and cutaneous metastatic lesions." (PMID 28671620, 2017). "Concerning KLK6, a controversial study reported that this protein is not expressed by melanoma cells but rather by keratinocytes and stromal cells of the microenvironment." (PMID 28636767, 2017). "This study was the first to report a coordinated decrease in mRNA expression levels of hKLKs (KLK6, KLK7, KLK8 and KLK13) as melanoma cells emerges from primary to metastatic phenotype, suggesting a role of these proteases in the epithelial-mesenchymal transition of primary melanoma cells." (PMID 22032772, 2011). "In addition, Western blot analysis showed that TNF-α and CXCL1 protein were detected in tumor tissues from WT mice injected with B16F10 melanoma but not in those from KLK6−/− mice injected with B16F10 cells." (PMID 36552865, 2022). "For melanoma progression category (T3, T4 and MM), only genes ontologically-related to hKLKs (EVPL, KLK6, KLK7, KLK8, KLK13 and SERPINB13) showed a positive and high correlation coefficient (mean of 0.971) in T4 thick melanomas (depth > 4.0 mm), but not in metastatic tumors (MM)." (PMID 22032772, 2011).
Parkinson disease (10 papers, 2015 to 2025). A progressive degenerative disorder of the central nervous system characterized by loss of dopamine producing neurons in the substantia nigra and the presence of Lewy bodies in the substantia nigra and locus coeruleus. "Several studies on Parkinson's disease have implicated KLK6 in the degradation of intracellular α-synuclein." (PMID 26783378, 2015). "Current evidence indicates that extracellular aggregation of α-synuclein may be implicated in the pathogenesis of Parkinson’s disease and that KLK6 mediates its degradation directly and via a proteolytic cascade that involves MMPs." (PMID 32655372, 2020). "Mouse models with the knockout of the Klk6 gene have become a valuable tool for understanding KLK6 function in several human diseases (e.g., spinal cord injury, Parkinson’s disease, skin regeneration, Netherton syndrome)." (PMID 39594797, 2024). "KLK6 is one of the most abundant serine proteases in the CSF and its levels are reduced in patients with synucleinopathy, including Parkinson’s disease." (PMID 32655372, 2020). "Our findings open the possibility to exploit KLK6 as a novel therapeutic target for Parkinson disease and other synucleinopathies." (PMID 27845893, 2017). "In synucleinopathies, including Parkinson disease, the levels of KLK6 inversely correlate with α-synuclein in CSF." (PMID 27845893, 2017). "Recent findings revealed that α-synuclein, a protein involved in the pathology of Parkinson’s disease, is also a potential KLK6 substrate." (PMID 27186164, 2016). "The dysregulation of certain KLKs, that is, KLK1 and KLK7, but mainly KLK6 and KLK8, may contribute to the development of neurodegenerative or neurological disorders such as Alzheimer’s and Parkinson’s diseases, memory disorders or mental illness." (PMID 32655372, 2020).
prostate carcinoma (10 papers, 2002 to 2026). A carcinoma that arises from epithelial cells of the prostate gland. "KLK6 blood levels in patients with intermediate-risk prostate cancer treated with definitive EBRT significantly decreased at 2 and 12 months following RT compared with the baseline levels before the initiation of RT, but not to undetectable levels." (PMID 33490732, 2021). "KLK6 and KLK12 are reported to be markers associated with highly aggressive prostate cancer, but future studies are still needed to validate these findings." (PMID 37240308, 2023). "Herein, we first demonstrated how miR-378 exerts anti-prostate cancer (PCa) actions by influencing multiple target genes, including KLK2, KLK4, KLK6, and KLK14, which are implicated in PCa development, cell proliferation, and cell survival." (PMID 35681793, 2022). "The successful application of KLK3 (also known as prostate-specific antigen) for prostate cancer diagnosis and prognosis has led to studies concerning KLK6 as a potential biomarker for cancers." (PMID 24669031, 2014). "Nasser et al68 investigated the role of KLK6 in prostate cancer." (PMID 33490732, 2021). "This indicates that KLK6 is secreted from the prostate gland and could potentially be a part of a panel of markers that tests the response to RT in patients with prostate cancer." (PMID 33490732, 2021). "A list of candidate biomarkers was chosen according to a set of criteria, highlighting KLK6, a protein that belongs to the 15-member KLK family in which KLK3 (also known as prostate-specific antigen) is the most useful marker for the early detection of prostate cancer." (PMID 24669031, 2014).
dementia (9 papers, 2014 to 2026). Loss of intellectual abilities interfering with an individual's social and occupational functions. "With respect to central nervous system processes, KLK6—a serine protease that degrades for example amyloid precursor protein and alpha-synuclein —was associated with lithium use, which is interesting as lithium has shown protective effects for dementia." (PMID 35136035, 2022). "Neurogranin (NRG), TAR DNA-binding protein 43 (TDP43), chitinase 3-like 1 (YKL40, cartilage glycoprotein-39), and kallikrein 6 (KLK6) are often found in classical AD and other dementias." (PMID 34944606, 2021). "Previous studies showed that KLK6 was related to neuroinflammation and neurodegenerative diseases, as it was induced in the mild cognitive impairment group compared to the dementia group." (PMID 33276674, 2020). "Increased plasma KLK6 levels in patients with AD with a more advanced disease stage suggest KLK6 as a potential biomarker in patients with AD with more severe dementia." (PMID 29378650, 2018). "Among the top 20 proteins in the brain aging clock, those associated with at least two dementia phenotypes included glial fibrillary acidic protein (GFAP), neurofilament light chain polypeptide (NEFL), brevican (BCAN), kallikrein-6 (KLK6) and synaptotagmin-1 (SYT1)." (PMID 41299092, 2026). "KLK6 participates in astrogliosis by activating PAR-1 in astrocytes, and an elevated PAR-2 expression has been described in neurons of HIV-1 patients associated to dementia, and its activation seems to prevent neuronal cell death." (PMID 32655372, 2020).
lung carcinoma (9 papers, 2014 to 2022). "The S100A6 protein, which was found to be an interacting partner of SPRR3 and SPRR1A in KLK6 high group, has been associated with cells motility and tumor metastasis in cervical cancer cells and lung carcinoma." (PMID 34065672, 2021). "KLK6 mRNA expression is enhanced in patients with lung cancer and is an indicator of tumor proliferation and poor OS." (PMID 36052170, 2022). "The over‐expression of KLK6 transcript and protein has been recognized in numerous cancer types, such as breast, renal, pancreatic, ovarian, colorectal, and lung cancer." (PMID 34151535, 2021). "Consistently, it was previously reported that high levels of KLK6 promote resistance to apoptosis in A549 lung cancer cells." (PMID 30980596, 2019). "In contrast to our data, KLK6-induced nuclear translocation of β-catenin was demonstrated in mouse keratinocytes and human lung cancer cell lines in vitro, further supporting a diverse and context dependent function of KLK6 in malignant progression." (PMID 25990935, 2015).